CRP (C-reactive protein)
Diseases named in the same sentence as CRP in open-access papers (continued):
Sharing a sentence is not in itself a finding about the gene and the disease.
myocardial infarction (continued). "The results of the AMORIS and INTERHEART studies demonstrated that the apoB : apoA-I ratio was the strongest predictor for myocardial infarction among all investigated variables and most importantly, like CRP, was able to identify subjects at high risk even when LDL-C values were considered normal." (PMID 23125484, 2012). "Epidemiological findings in the region of Augsburg, Germany, showed that elevated levels of PM are associated with an increased incidence of myocardial infarction and also with increased levels of markers indicative for early systemic effects, like CRP and IL-6, or with plasma viscosity." (PMID 20920269, 2010). "Elevated plasma levels of CRP have been repeatedly found in patients with cardiovascular disease (CVD) and myocardial infarction, and it has been proposed that CRP is an independent risk factor of CVD, although the pathogenic and clinical significance of CRP remains controversial." (PMID 20074603, 2010). "Recent scientific evidence together with the joint AHA/CDC guidelines, however, strongly recommends that in performing a global risk assessment for CAD, new risk factors to measure heart attack risk such as circulating markers of inflammation like C-reactive protein (CRP)should be used." (PMID 17971195, 2007). "Importantly, high CRP levels in the context of myocardial infarction may increase myocardial damage independent from the cause of the CRP rise." (PMID 39211771, 2024). "Since the rs1205 TT genotype results in lower serum CRP levels and is associated with lymph node metastasis in this form of cancer, rs1205 may be associated with thoracic esophageal squamous cell cancer, myocardial infarction, systemic lupus erythematosus and lupus nephritis." (PMID 38184750, 2024). "In addition, IL-6 and CRP may be associated with diagnosis, risk stratification and prognosis in patients with acute myocardial infarction, and both are also significantly upregulated in acute coronary syndromes." (PMID 37485268, 2023). "Additionally, short-term mortality post-acute myocardial infarct is associated with CRP responses." (PMID 36177015, 2022). "Several investigations have associated elevated levels of CRP with future cardiovascular events, including acute myocardial infarction (MI), stroke, and peripheral artery disease." (PMID 35888650, 2022). "Several prospective clinical trials have documented the association of elevated CRP with an increased risk of stroke, peripheral arterial disease, myocardial infarction (MI), and sudden death, both in men and women." (PMID 34754275, 2021). "In recent years, more sensitive assays have been developed and high‐sensitivity CRP determination is considered as an indicator of low‐grade systemic inflammation that may be a useful predictor for the risk of atherosclerosis and myocardial infarction." (PMID 32246830, 2020). "Measurement of CRP is useful for the detection and evaluation of infection, tissue injury, inflammatory disorders, and associated diseases, and it has been shown that CRP levels are of prognostic value in patients with myocardial infarction and unstable angina." (PMID 26903710, 2016). "The ongoing Canakinumab Anti-inflammatory Thrombosis Outcomes Study (CANTOS) is just testing whether reducing inflammation among men and women who have had a prior heart attack and have CRP > 2 ngm/ml can reduce the risk of another cardiovascular event happening in the future." (PMID 25969671, 2015). "High levels of C-reactive protein have been associated with an increased risk of in-hospital and later new coronary events in patients with unstable angina, as well as with increased long term risk of death and myocardial infarction in apparently normal subjects." (PMID 23819098, 2013).
myocardial infarction (continued). "The fourth quartile of peak CRP was associated with poorer outcome as compared to the first quartile in a multivariate Cox-regression analysis, with a hazard ratio of 2.0 (95% CI 1.1–3.7) for the occurrence of death, myocardial infarction and ischemic cerebral events." (PMID 19583836, 2009). "This is in line with a large meta-analysis comprising 18,715 individuals, where Liu et al10 demonstrated that elevated CRP levels are a significant predictor of MACE events in patients with acute myocardial infarction undergoing PCI." (PMID 40080922, 2025). "In myocardial infarction, cfDNA peaks early, indicating acute injury, while CRP rises later, reflecting prolonged inflammation." (PMID 40282303, 2025). "As a reliable inflammatory biomarker, CRP is strongly associated with the increased risk and severity of AKI in patients with acute myocardial infarction or group A streptococcal bacteremia." (PMID 40860683, 2025). "In our study, B-type natriuretic peptide ( diagnoses heart failure, C-reactive protein diagnoses systemic inflammation, and cTnI diagnoses myocardial infarction (the highest AUC = 0.94)." (PMID 41480420, 2025). "In human medicine, elevated CRP levels during HF are well documented, as tissue necrosis is a major trigger for CRP release and serves as a key prognostic factor in acute myocardial infarction." (PMID 40988759, 2025). "Elevated CRP levels on admission in ACS patients are strongly associated with worse short- and long-term cardiovascular outcomes, including higher risk of death, myocardial infarction, heart failure, and MACE." (PMID 41511355, 2025). "High levels of inflammatory markers like C-reactive protein (CRP) were found to predict an unfavorable disease course during acute myocardial infarction (AMI)." (PMID 41517355, 2025). "The results of the sensitivity analysis showed the stability of the effect of CRP level on fQRS in myocardial infarction." (PMID 41303859, 2025). "Studies have shown that elevated CRP levels are associated with an increased risk of CVD, particularly in patients with acute myocardial infarction, where changes in CRP levels reflect the degree of the inflammatory response." (PMID 41343565, 2025). "This landmark study evaluated the effects of IL-1β inhibition using canakinumab in patients with a history of myocardial infarction and elevated high-sensitivity CRP (hs-CRP) levels." (PMID 40217801, 2025). "Experimental data suggested that inhibiting C-reactive protein in acute myocardial infarction reduces myocardial damage." (PMID 40080922, 2025). "In conclusion, this single-center retrospective study demonstrates that the CRP-TyG index (CTI) serves as a valuable early biomarker for hepatic synthetic dysfunction in post-myocardial infarction ICU patients within 24 h." (PMID 41458520, 2025). "Higher levels of CRP are observed in both myocardial infarction and heart failure, which indicates that systemic inflammation is in progress." (PMID 41480420, 2025). "The findings from the selected literature were critically analyzed and synthesized to provide an updated and integrative overview of CRP’s clinical and biological relevance in acute myocardial infarction." (PMID 40649166, 2025). "The CANTOS trial included patients with a history of myocardial infarction and elevated baseline C-reactive protein (CRP)." (PMID 40636825, 2025). "Beyond CRP, both IL-1ra and resistin exhibit specific temporal patterns during acute myocardial infarction." (PMID 41226718, 2025). "C-reactive protein (CRP) has emerged as a valuable biomarker in acute myocardial infarction (AMI), offering multiple insights into diagnosis, prognosis, and therapeutic strategies." (PMID 40649166, 2025). "Elevated baseline plasma concentrations of CRP have been shown to independently predict incident atherothrombotic events, including myocardial infarction and ischemic stroke." (PMID 41226611, 2025).
myocardial infarction (continued). "C-reactive protein (CRP) plays a detrimental role in acute myocardial infarction (AMI) by mediating tissue damage and potentially worsening clinical outcomes." (PMID 41511355, 2025). "Elevated levels of both Hcy and hs-CRP are associated with greater CHD severity, particularly in patients with acute myocardial infarction or unstable angina pectoris (UAP), further highlighting their roles as predictors of disease severity." (PMID 39898976, 2025). "A comprehensive narrative literature review was conducted to synthesize the current knowledge on the role of C-reactive protein (CRP) in acute myocardial infarction (AMI)." (PMID 40649166, 2025). "In one study, the mean CRP level was 1.89 mg/L upon hospital admission for myocardial infarction, reaching a peak of 12.10 mg/L during hospitalisation, and subsequently decreasing to 1.24 mg/L after one month." (PMID 38921434, 2024). "This study aims to investigate the correlation between hs-CRP and HbA1c levels in patients with acute myocardial infarction (AMI) and T2DM, focusing on their impact on six-month mortality outcomes." (PMID 39286672, 2024). "Expression of CARD8 mRNA and protein has been identified in human atherosclerotic lesions, and the truncated T30A variant (rs2043211) of CARD8 has been associated with lower C-reactive (CRP) and MCP-1 levels in myocardial infarction patients." (PMID 38350853, 2024). "High levels of CRP in peoplewith low blood pressure and a recent heart attack history can predict futurecoronary events." (PMID 39076491, 2024). "For patients with a significant elevation CRP after myocardial infarction, it is important to take echocardiographic examinations more frequently to prevent cannot resolve of the thrombus once it is formed." (PMID 38811882, 2024). "Proteins involved in the complement and coagulation cascades, like MASP2, CRP, FCN3, and MBL2, were elevated, underlining the known importance of innate immunity and inflammation early in myocardial infarction." (PMID 39513871, 2024). "In terms of serum markers, creatine phosphokinase isoenzyme CK-MB, troponin I (TnI/T) and high-sensitivity C-reactive protein are useful for early myocardial infarction diagnosis." (PMID 39660115, 2024). "For instance, C-reactive protein (CRP) is the most predictive biomarker of Acute Myocardial Infarction." (PMID 38894085, 2024). "Even after adjusting for baseline confounders, CRP levels remained an independent predictor of MACE, with higher values linked to significantly greater all-cause mortality and myocardial infarction rates during the follow-up." (PMID 39323757, 2024). "In the CANTOS trial, canakinumab (an IL-1β targeting antibody) reduced the number of major cardiovascular events in CKD patients with a prior myocardial infarction and high inflammatory (CRP) status." (PMID 38416185, 2024). "In this study, patients with a history of myocardial infarction (MI) and elevated levels of high-sensitivity C-reactive protein (hs-CRP) (≥2 mg/dl) were randomly assigned to receive either canakinumab [an interleukin-1β (IL-1β) monoclonal antibody] or placebo." (PMID 38993522, 2024). "Some studies have shown a positive correlation between the serum value of HGF and CRP in patients with other acute or chronic conditions, e.g., chronic liver disease and chronic renal failure requiring renal replacement, or after acute myocardial infarction." (PMID 39457546, 2024). "The current study showed that all CVD groups (myocardial infarction and heart failure) exhibited higher CRP levels compared with the healthy controls." (PMID 35997998, 2023). "The concentration of C-reactive protein in plasma increases rapidly and significantly in cases of acute myocardial infarction, trauma, infection, inflammation, surgery, and malignant tumors." (PMID 36927471, 2023). "After a heart attack, CRP activates the complement system on ischemic myocytes, leading to their lysis." (PMID 37376511, 2023).
myocardial infarction (continued). "Typical cardiac biomarkers consisting of CRP, TNFα, CA-125, cTnI, cTnT, myoglobin, and CK-MB have an important role in diagnosing myocardial infarction (AMI)." (PMID 36832048, 2023). "The percentage of myocardial infarction was 23 (3.2%) in the high CRP group compared to six (0.8%) in the normal group." (PMID 37273333, 2023). "As early as 1999, CRP was shown to induce cell death after acute myocardial infarction (AMI) in rats and this was found to be dependent on complement." (PMID 37626775, 2023). "Specifically, the rising CRP concentration after an acute myocardial infarction correlates significantly with the clinical outcome of the patient." (PMID 37626775, 2023). "In view of these observations, it was suggested several years ago that elevated CRP levels in acute myocardial infarction should be specifically reduced." (PMID 37626775, 2023). "Comparable CRP localization to necrotic cardiac muscle fibers was seen when myocardial infarction was induced by cardiac artery ligation." (PMID 36936978, 2023). "Lowering plasma CRP level with rat-specific ASO ISIS 197178 was associated with reduction of infarct size and improved cardiac function in a rat model of myocardial infarction." (PMID 37564640, 2023). "Following acute myocardial infarction, CRP concentrations were found to rise exponentially, with a mean doubling time of 8.2 h." (PMID 36936978, 2023). "The levels of integrin β1–3, interleukin-6 (IL-6), and C-reactive protein were significantly higher in patients with acute myocardial infarction (AMI; n = 44) and acute VTE (n = 43) compared to healthy controls (n = 33)." (PMID 37998519, 2023). "Elevated levels of pro-inflammatory cytokines C-reactive protein (CRP), IL-6, and TNF have been shown to be associated with the risk of myocardial infarction and mortality." (PMID 36769308, 2023). "Age, sex, smoking, SBP, HbA1c, antihypertensive treatment, BMI, CRP, eGFR, cholesterol, and previous myocardial infarction or ischemic stroke." (PMID 37485272, 2023). "CRP is a highly sensitive protein with an increased plasma concentration during myocardial infarction, stress, trauma, infection, inflammation, surgery and neoplastic proliferation." (PMID 36843786, 2023). "Previous studies showed the relationship between early increased CRP level and left ventricular systolic function, future heart failure, and mortality in patients who had a myocardial infarction." (PMID 36741499, 2023). "Independent of other confounding factors, periodontal disease raises C reactive protein levels in individuals with acute myocardial infarction, becoming an additional goal for minimizing potential risks in acute myocardial infarction (AMI) survivors." (PMID 37915876, 2023). "CRP is used as an individual marker for atherogenesis, myocardial infarction, stroke, and cardiac arrest due to coronary heart and peripheral arterial diseases." (PMID 39554800, 2023). "Increased levels of inflammatory markers like C-reactive protein (CRP) and interleukin-6 (IL-6) are closely linked to a higher risk of heart attacks." (PMID 38292979, 2023). "Regardless, detection of CRP during risk assessment of CVD, namely, myocardial infarction, greatly improves its prognostic power, and can help prevent another event within the subsequent 10 years." (PMID 36834801, 2023). "Another study that included patients after acute myocardial infarction testedthe ability of colchicine to reduce the levels of CRP." (PMID 39076864, 2023). "It has been known for decades that CRP increases during myocardial infarction and that the magnitude is related to infarction size." (PMID 35203485, 2022). "Sensitive determination of C-reactive protein (CRP) is of great significance because it is an early indicator of inflammation in cardiovascular disease and acute myocardial infarction." (PMID 36432268, 2022).
myocardial infarction (continued). "The CAMI-1 investigators evaluated the feasibility and safety of CRP apheresis to reduce myocardial infarct size after ST segment elevation myocardial infarction (STEMI) as determined by CV magnetic resonance." (PMID 35192610, 2022). "In the CANTOS trial, the administration of Canakinumab, an antagonist of IL-1beta, reduced the recurrence of cardiovascular events in patients with a history of myocardial infarction and CRP values > 2 mg/L as compared to a placebo." (PMID 36499242, 2022). "After myocardial infarction diabetic patients also show higher inflammatory activity measured by elevated markers of inflammation (CRP and IL-6)." (PMID 35845058, 2022). "Our study proved that there was a positive correlation between MPO and hs-CRP, leukocyte count, neutrophils, and fibrinogen, reflecting the aggravation of inflammatory state during myocardial infarction." (PMID 35419382, 2022). "Elevated PGE2 levels are one of the most important markers, along with C-reactive protein (CRP), IL-6, VCAM-1, myeloperoxidase, secretory PLA2 and COX-2, indicating high risk of myocardial infarction and associated with poor prognosis." (PMID 35163232, 2022). "Although there is no doubt about the early involvement of inflammation in endothelial dysfunction and atherogenesis, only 14% of patients with undisputed vascular inflammation, for example on admission for myocardial infarction, have elevated CRP." (PMID 35933413, 2022). "The first and also the only clinical study on CRP apheresis in STEMI patients published up to the present day is the C-reactive protein apheresis in Acute Myocardial Infarction-1 (CAMI-1) study." (PMID 35407379, 2022). "In contrast, IL-1β inhibition improves adverse cardiac remodeling after acute myocardial infarction, which includes left ventricle end-systolic volume index, change in CRP levels, and proinflammatory response." (PMID 35425785, 2022). "In this case control study aimed to investigate the correlation of H-FABP with CKMB, hs-CRP and cTnT in young Myocardial Infarction Patients." (PMID 37168777, 2022). "More importantly, CRP is designated as an early indicator of inflammation in cardiovascular diseases and acute myocardial infarction." (PMID 36432268, 2022). "Many single nucleotide polymorphisms are shared by both diseases and HLA DRB1*01 haplotype, which is linked to RA susceptibility, has been associated with C-reactive protein (CRP) levels and the risk of myocardial infarction in general population." (PMID 36352850, 2022). "Univariate regression analyses showed that smoking, high CRP and neutrophil to lymphocyte ratio levels were correlated with recurrent myocardial infarction in the long term follow up." (PMID 34326966, 2021). "In conclusion, our study demonstrated that the probability of clinical deterioration for a given AI-based severity score value increases in the presence of immunodeficiency, prior myocardial infarction and increasing CRP levels." (PMID 34842822, 2021). "This problem can be solved by CRP apheresis, which removes CRP from the blood plasma after myocardial infarction, significantly reducing the infarct area and improving LVEF." (PMID 34707513, 2021). "The investigators of the recently published “CRP apheresis in Acute Myocardial Infarction (CAMI-1)” study moved downstream of IL-6 in the inflammatory cascade, directly targeting the inflammatory marker high-sensitivity C-reactive protein (hsCRP)." (PMID 35087883, 2021). "In the CAMI-1 study, the CRP gradient was suggested to correlate with a greater extent of myocardial infarct size (IS) and reduced LVEF." (PMID 34884196, 2021). "It is less known that CRP mediates tissue damage in acute myocardial infarction (AMI) thus potentially worsening prognosis." (PMID 33778017, 2021). "ROC curves were created using the following parameters: prior myocardial infarction, immunodefficiency, CRP and DL severity score, which can be seen in Figure A4 and Figure A5." (PMID 34842822, 2021).